C11orf16 (chromosome 11 open reading frame 16)
Tractability: No criterion of Open Targets' tractability assessment is met for any kind of drug.
Gene: Protein-coding gene on chromosome 11 (8,920,076 to 8,933,006, reverse strand). Ensembl gene ENSG00000176029.
Subcellular location (Human Protein Atlas): Endoplasmic reticulum; Vesicles
Genetic constraint (gnomAD): Loss-of-function variants: 35 observed, 44.2 expected, observed/expected ratio (o/e) 0.79, 90% interval 0.6 to 1.05. The upper end of that interval is the gene's LOEUF score, 1.05, which puts it in group 4 of 6, group 1 being the genes least tolerant of losing a copy. Missense variants: 557 observed, 556.64 expected, observed/expected ratio (o/e) 1, 90% interval 0.93 to 1.07. Synonymous variants: 212 observed, 219.13 expected, observed/expected ratio (o/e) 0.97, 90% interval 0.86 to 1.08.
Homologues: Orthologues: macaque C14H11orf16 (91% identical), rabbit C11orf16 (65% identical), dog C11orf16 (63% identical), guinea pig C11orf16 (60% identical), chimpanzee C11H11orf16 (58% identical), mouse BC051019 (54% identical), rat C1h11orf16 (53% identical), tropical clawed frog c4h11orf16 (29% identical), zebrafish si:dkey-8l13.5 (20% identical).